EGFR (epidermal growth factor receptor)
Diseases named in the same sentence as EGFR in open-access papers (continued):
Sharing a sentence is not in itself a finding about the gene and the disease.
triple-negative breast carcinoma (continued). "The development of anti-EGFR directed therapy in triple negative breast cancer has been supported by the availability of some preclinical data." (PMID 21457545, 2011). "Overexpression of EGFR (HER1) is common in the subgroup generally referred to as “triple negative breast cancer” (TNBC); these tumors lack the ER, the PgR, and have normal human epidermal growth factor 2 receptor (HER2/neu) levels." (PMID 22295238, 2011). "Since most basal-like tumors express EGFR, it seemed of interest to investigate the mutational status of KRAS in such tumors to provide scientific evidence for the evaluation of anti-EGFR therapies in the management of triple-negative breast cancer." (PMID 20385028, 2010). "Breast tumour tissue microarrays were profiled to evaluate the frequency to which EGFR and YB-1 are expressed in triple negative breast cancers." (PMID 17875215, 2007). "Specifically, Naringenin-7-O-β-D-glucoside induces dose-dependent cytotoxicity in MDA-MB-231 triple-negative breast cancer cells, accompanied by increased DNA fragmentation and reduced expression of the epidermal growth factor receptor (EGFR), suggesting interference with tumor progression pathways." (PMID 40942095, 2025). "A recent study identified a conserved four-amino acid (NPGF) intracellular motif in VISTA that interacts with NUMB and sequesters it at endosomes, impairing epidermal growth factor receptor (EGFR) signaling and cellular proliferation in triple-negative breast cancer (TNBC)." (PMID 41233805, 2025). "A more recent strategy involves an advanced ADC that targets EGFR on the tumor cell surface while delivering a CDK inhibitor to disrupt dysregulated cell cycle signaling, offering a potential treatment option for patients with EGFR-expressing, therapy-resistant triple-negative breast cancer (TNBC)." (PMID 41007788, 2025). "Moreover, EGF-polymeric micelles exerted cytotoxic effects on MDA-MB468 human triple-negative breast cancer cells, which are generally resistant to EGFR-targeting anti-cancer drugs." (PMID 41140511, 2025). "This ultimately could shift the paradigm for the treatment regimen in this patient population with EGFR amplification, especially triple negative breast cancer patients who have fewer targeted therapy options." (PMID 40501689, 2025). "Moreover, NONO contributes to oncogenesis, chemotherapy resistance, and poor prognosis in triple-negative breast cancer (TNBC) by modulating Epidermal Growth Factor Receptor (EGFR) and Signal Transducer And Activator Of Transcription 3 (STAT3) stability." (PMID 40943463, 2025). "While we looked for patterns based on molecular subtypes, the five triple negative breast cancer patients and six patients with targetable EGFR mutations did not demonstrate any clear patterns of response." (PMID 40877204, 2025). "This hypothesis is consistent with ambrosin's inhibition of EGF-induced auto-phosphorylation of the critical Y1068 residue of EGFR in bladder cancer cells and, to a lesser extent, in triple negative breast cancer cells." (PMID 40754248, 2025). "EGFR has been indicated to be a potential drug target for triple-negative breast cancer cases." (PMID 39405290, 2024). "However, Tinagl1 suppresses tumor progression and metastasis by inhibiting integrin/FAK and EGFR downstream signaling pathways in triple-negative breast cancer." (PMID 38355577, 2024). "Also, tetravalent RNA aptamers against EGFR conjugated exosome using click chemistry were proved to enhance targeting in EGFR-overexpressing triple negative breast cancer." (PMID 38172932, 2024). "The authors identified a “high-risk” profile for triple-negative breast cancer (TNBC), characterized by low expression levels of PD-L1 and androgen receptor (AR), alongside high expression levels of epidermal growth factor receptor (EGFR) and Ki67." (PMID 39682581, 2024). "EGFR is highly expressed in most triple-negative breast cancer (TNBC) patients." (PMID 38604999, 2024).
triple-negative breast carcinoma (continued). "However, clinical studies evaluating the use of the anti-EGFR and anti-c-Met inhibitors in triple-negative breast cancer often demonstrate an initial response among a subset of patients followed by the development of treatment resistance." (PMID 37760847, 2023). "The resistance mediators identified in this study could be applied in the future to develop new therapeutic strategies for counteracting resistance to EGFR and c-Met inhibitors in triple-negative breast cancer." (PMID 37760847, 2023). "Additionally, these therapies are ineffective in tumors where EGFR is found predominantly in the nucleus, as can be found in triple negative breast cancer (TNBC)." (PMID 37720348, 2023). "Moreover, HR+/HER2- and basal-like tumors are biologically more similar to triple-negative breast cancers, characterized by increased expression of cyclin E1, EGFR, and p16 and low expression of ER1, PGR1, and Forkhead box1." (PMID 35806079, 2022). "Furthermore, epidermal growth factor receptor is methylated by PRMT1 in triple-negative breast cancer cells, and methylation enhances epidermal growth factor receptor activity." (PMID 36152748, 2022). "Transcriptomic analysis of mice bearing a triple-negative breast cancer with an acquired resistance to anti-EGFR CAR T cells showed that treatment with EGFR-specific CAR T cells induced immunosuppressive genes that were associated with CAR T cell-activated enhancers." (PMID 35203517, 2022). "Concomitant inhibition of the cGAS-STING axis and growth factor signaling mediated by the epidermal growth factor receptor (EGFR) synergistically suppressed the development of tumor organoids derived from primary tumor tissues of triple-negative breast cancer (TNBC)." (PMID 35992877, 2022). "Furthermore, DL demonstrated high activity against EGFR, therefore, we can suppose that this compound can be a drug candidate against triple negative breast cancer." (PMID 35889371, 2022). "For example, scRNA-seq was used to assess the triple-negative breast cancer patient derived cells that respond to epidermal growth factor receptor (EGFR) therapy and found an increased presence of enhanced stem-cell-like/mesenchymal characteristics in these cells." (PMID 35892890, 2022). "The triple negative breast cancer (TNBC) cell line MDA-MB-231 is strongly dominated by EGFR." (PMID 35625984, 2022). "The use of alternatively targeted imaging agents to identify triple negative breast cancer may be promising, as EGFR overexpression is seen in 57% of triple negative breast cancers." (PMID 33803201, 2021). "Indeed, EGFR activation with EGF reduced cellular sensitivity to CHK1 inhibition, and conversely, inhibition of EGFR with erlotinib enhanced cellular cytotoxicity with prexasertib in several in vitro and in vivo models of triple negative breast cancer." (PMID 34532658, 2021). "This promotes EGFR recycling and sustained signaling in triple-negative breast cancer." (PMID 33411917, 2021). "It is exciting to speculate that the phosphorylation of this residue could coincide with de novo EGFR inhibitor resistance in metastatic breast cancer, in particular triple-negative breast cancer that typically express high levels of EGFR." (PMID 31597954, 2020). "Notably, Arf1 has been reported to be activated downstream of the EGFR in triple negative breast cancer cells (TNBC) cells." (PMID 31991585, 2020). "Furthermore, Icaritin and Cy-3-glu are associated with EGFR-dependent signaling inhibition and apoptosis of MDA-MB-231 triple negative breast cancer cells." (PMID 32526980, 2020). "Furthermore, they showed that metformin targets the cholesterol biosynthesis pathway and stabilizes GM1 lipid rafts, reducing membrane EGFR (epidermal growth factor receptor) signaling and its activation in triple-negative breast cancer." (PMID 32911743, 2020). "High EGFR gene copy number predicts poor outcomes in triple-negative breast cancer." (PMID 31896739, 2020).
triple-negative breast carcinoma (continued). "Furthermore, we reveal that NP-G2-044 decreases the cell proliferation and primary tumor growth of activated B-cell diffuse large B-cell lymphoma, diffuse mixed lineage lymphoma, and epidermal growth factor receptor (EGFR)-high triple-negative breast cancer." (PMID 32824026, 2020). "Furthermore, it was revealed that cSBL decreases the expression of the epidermal growth factor receptor (EGFR/HER1) in triple-negative breast cancer cells." (PMID 30347895, 2018). "This approach could be particularly effective in tumors characterized by high levels of EGFR and Snai2, such as triple-negative breast cancer." (PMID 29674627, 2018). "Differential activity of zoledronic acid in the two cell lines studied may be explained through pathway addiction to EGFR and hence Ras activity in triple-negative breast cancer." (PMID 30555636, 2018). "It was shown that siRNA effectively suppressed resistance of TNBCs to gefitinib and, consequently, enhanced the efficacy of the treatment demonstrating a high potential of liposomal EGFR siRNA in combination with liposomal gefitinib for treatment of triple-negative breast cancer." (PMID 29978332, 2018). "More than 78% of triple negative breast cancer cases show overexpression of EGFR." (PMID 29949609, 2018). "The level of EGFR phosphorylation would significantly increase on the exposure of cells to the recombinant PKM2 protein, and the secretion of PKM2 would induce EGFR phosphorylation and activate the EGFR downstream signaling in triple-negative breast cancer cells." (PMID 29299177, 2017). "Aberrant Ras-MAPK signaling from receptor tyrosine kinases (RTKs), including epidermal growth factor receptor (EGFR) and human epidermal growth factor receptor-2 (HER2), is a hallmark of triple negative breast cancer (TNBC); thus providing rationale for targeting the Ras-MAPK pathway." (PMID 29113345, 2017). "Estrogen receptor-, progesterone receptor- and HER2-negative breast cancers, also known as triple-negative breast cancers (TNBCs), have poor prognoses and are refractory to current therapeutic agents, including epidermal growth factor receptor (EGFR) inhibitors." (PMID 27462789, 2016). "Moreover, EGFR signaling is commonly upregulated in epithelial cancers, such as triple negative breast cancer, that have a stem cell-like molecular profile." (PMID 25437306, 2014). "Interestingly, increased HER family ligands were shown to mediate resistance to anti-AKT inhibitors in triple-negative breast cancer cells, which was abrogated by targeting both EGFR and HER3 with a dual receptor ligand-blocking antibody." (PMID 25344208, 2014). "In addition to c-Src, EGFR is frequently overexpressed in aggressive breast tumors and triple negative breast cancer cell lines, as are a number of downstream components of EGF signaling pathways." (PMID 23762409, 2013). "Moreover, the resistance to EGFR TKI is a major clinical problem in treating EGFR-overexpressing triple-negative breast cancer (TNBC)." (PMID 23593472, 2013). "EGFR has been considered as a sensible target in basal-like and triple negative breast cancer." (PMID 23039971, 2012). "However, BRC-230, presented a genetic amplification of EGFR and concomitant overexpression of the protein as observed in triple-negative breast cancers." (PMID 23173568, 2012). "Interestingly, in all three models of triple negative breast cancer used in this study, a similar level of cytotoxicity was observed despite differential EGFR expression." (PMID 23071597, 2012). "In vitro studies on effects of EGFR inhibition in triple negative breast cancer cell lines revealed that gefitinib inhibited EGFR phosphorylation, which led to reduced signaling by the mitogen activated protein kinase (MAPK) and Akt pathway and causing cell cycle arrest at G1 phase." (PMID 21457545, 2011).
triple-negative breast carcinoma (continued). "Similarly, GABRP sustains the self-renewal capacity of triple-negative breast cancer stem cells via EGFR pathway activation, while also governing airway epithelial progenitor differentiation by regulating goblet cell formation, thereby maintaining tissue homeostasis." (PMID 40901676, 2025). "Also, EGFR copy number gain might be one of the accumulating genetic alterations during tumor progression and EGFR activation induced by EGFR copy number gain may contribute to tumor aggressiveness in triple-negative breast cancer." (PMID 38674331, 2024). "Furthermore, we have shown that NP-G2-044 decreases the growth of U2932 and Ly10 cells (both are ABC-subtype of DLBCL cells) and HT cells (a diffuse mixed lymphoma cell), as well as MDA-MB-468 and BT-20 cells (both are EGFR-high triple-negative breast cancer cells)." (PMID 32824026, 2020). "In this context, CD90 could be a meaningful molecule in the biology of triple negative breast cancer since its overexpression was able to increase the proliferative cell rate, activate the EGFR pathway and, also, promote the invasion and migratory capacity in vitro and in vivo." (PMID 29949609, 2018). "Thus, the specific targeting of the EGFR and c-Met may be a useful strategy against triple negative breast cancer." (PMID 30227653, 2018). "Thus, our findings may help to consider use of PHD2 inhibitors together with anti-EGFR antibodies, which alone have limited therapeutical benefit for the treatment of triple negative breast cancers." (PMID 28038470, 2017). "MDA-231 cells act as a model for triple negative breast cancers, so these findings raise the possibility that interventions that could reduce EGFR expression in triple-negative breast cancer cells might provide therapeutic benefit to patients with metastatic disease." (PMID 22276166, 2012). "BACKGROUND: Epidermal growth factor receptor (EGFR), characterized by its high positivity rate and strong specificity in triple-negative breast cancer (TNBC), has long been recognized as one of the characteristics of this subtype." (PMID 41814321, 2026). "The epidermal growth factor receptor (EGFR, PDB ID: 4I23) kinase domain is another important target, as EGFR is frequently overexpressed in triple-negative breast cancer, a highly aggressive and difficult-to-treat subtype." (PMID 40430480, 2025). "Mechanistic alignment with tumor vulnerabilities—including redox addiction, ferroptosis resistance, and immune evasion—supports its relevance for triple-negative breast cancer (TNBC) and EGFR-mutant NSCLC." (PMID 41228309, 2025). "Another experimental therapy undergoing testing by Acepodia is the epidermal growth factor receptor (EGFR)-targeting, ACC Vδ2 T cell therapy for use in combating colorectal, non-small cell lung, and triple-negative breast cancers." (PMID 40148988, 2025). "Although we did not conduct a standalone study to assess the individual contributions of the EGFR, cMET, and VEGFA arms in one NSCLC xenograft model using inert arm comparator molecules, we performed such study in a triple-negative breast cancer (TNBC) model." (PMID 40452841, 2025). "For triple-negative breast cancer (TNBC), combined treatment with autophagy inhibitors and the EGFR inhibitor gefitinib has also made positive progress." (PMID 41191140, 2025). "It was reported that triple-negative breast cancer cells (MDA-MB-468) can produce exosomes with encapsulated EGFR (protected from EGFR inhibitor), which can induce EGFR signaling in target cells, thereby promoting cancer progression or resistance to therapy." (PMID 40182844, 2025). "In triple-negative breast cancer (TNBC), EGFR amplification is present in nearly half of the cases and is associated with a poorer prognosis." (PMID 40364160, 2025).
triple-negative breast carcinoma (continued). "In triple-negative breast cancer cells, ablation of ICAM-1 expression suppresses while overexpression of ICAM-1 increases dimerization and phosphorylation of EGFR and activation of the EGFR-dependent signaling." (PMID 39594667, 2024). "Since a significant portion of migratory subtype tumors exhibit EGFR gains, therapies targeting EGFR, such as tyrosine kinase inhibitors (TKIs) could be effective in this patient subset, as is currently being investigated for triple-negative breast cancer (TNBC) patients." (PMID 38892065, 2024). "We previously reported on the interaction between CSMD1 and EGFR in triple-negative breast cancer and found that CSMD1 overexpression led to increased cell apoptosis following treatment with gefitinib, an EGFR inhibitor." (PMID 38561856, 2024). "The aptamer has excellent capability to recognize EGFR-positive cells belonging to different cancer types, including human epidermal growth factor receptor 2 (HER2)-positive tumors and triple-negative breast cancer (TNBC)." (PMID 38532439, 2024). "Despite promising efficacy in multiple tumors, these antibodies have had little effect in triple negative breast cancer (TNBC), even though these cancers express high levels of EGFR." (PMID 37720348, 2023). "Approximately half of the cases of triple-negative breast cancer (TNBC) and inflammatory breast cancer (IBC) overexpress EGFR." (PMID 36982173, 2023). "In fact, in triple-negative breast cancer cells, KISS1R was shown to regulate the transactivation of epidermal growth factor receptor (EGFR or ErbB1) via the actin cytoskeletal binding protein IQGAP111,22." (PMID 37640761, 2023). "Via EGFR signaling and EMT, 1,3-N-acetylglucosamine transferase 3 catalyzes the increase in interaction with PD-1 in triple-negative breast cancer." (PMID 36983711, 2023). "In triple-negative breast cancer cells, BBR reduces interleukin-8 (IL-8) expression by blocking the EGFR/MEK/ERK signaling pathway to prevent cell invasion and metastasis." (PMID 36937842, 2023). "In triple negative breast cancer (TNBC), FABP5 has been found to promote metastasis by inhibiting EGFR proteasome degradation." (PMID 37576389, 2023). "MDA-MB-231 is a triple negative breast cancer (TNBC) cell line which expresses EGFR and its bone-specific clone (MDA-MB-231-UR) is highly enriched for EGFR." (PMID 37399454, 2023). "We analyzed TCGA data from triple-negative breast cancer (TNBC) and we found a positive correlation between NUAK1 and EGFR expression." (PMID 38135881, 2023). "From a functional point of view, TINAGL1 is one of the most interesting up-regulated genes, since the corresponding protein-product suppresses the progression and diffusion of triple-negative breast-cancer via inhibition of the FAK and EGFR signaling pathways." (PMID 37951921, 2023). "The MDA-MB-231 is defined as a triple-negative breast cancer (TNBC) cell line, as it lacks ER, PR and EGFR." (PMID 37049894, 2023). "Contrastingly, for triple-negative breast cancer (TNBC), the phenotype EGFR was the best predictor at 0.78 followed by CDKN2A at 0.75." (PMID 37681908, 2023). "Another example is an anti-CL4 aptamer that inhibited triple-negative breast cancer (TNBC) cells and tumor growth by impacting the binding between epidermal growth factor receptor (EGFR) and integrin." (PMID 36544906, 2022). "A study suggests that anti-EGFR-directed radioimmunotherapy combined with radiosensitizing chemotherapy and PARP inhibitor is more effective in treating triple-negative breast cancer." (PMID 35663041, 2022). "Epidermal growth factor receptor (EGFR)-mediated PI3K/AKT, MAPK, and STAT3 signaling pathways are hyperactivated in the CD44+/CD24− BCSC population in MDA-MB-231, a human triple negative breast cancer cell line." (PMID 35805056, 2022).